FOXR2 (forkhead box R2)
Diseases named in the same sentence as FOXR2 in open-access papers (continued):
Sharing a sentence is not in itself a finding about the gene and the disease.
tumor (continued). "In the latest updated WHO CNS5 classification these two tumour types were incorporated as CNS neuroblastoma, FOXR2-activated and CNS tumour with BCOR internal tandem duplication (CNS BCOR ITD)." (PMID 36895035, 2023). "Among these, CNS neuroblastoma with FOXR2 activation shares the methylation profile and histological features of the tumor described here." (PMID 34468789, 2021). "In conclusion, we demonstrated that miR-202 functions as a tumor suppressor by inhibiting cell growth in EAC via downregulating oncogene-FOXR2 by directly targeting its 3′-UTR." (PMID 28827892, 2017). "Overall outcomes were significantly better than all other tumor types with FOXR2 overexpression." (PMID 40237561, 2025). "FOXR2 stimulated tumor growth in the olfactory bulb (OB) and brainstem (BS)." (PMID 39866234, 2025). "FOXR2 expression was similar between CNS NB and other tumor types (P = 0.82)." (PMID 40237561, 2025). "This expanded context makes clear that our observation of miR-152-3p downregulation is well-supported by the literature and may have functional consequences (de-repression of miR-152 targets like DNMT1 or FOXR2, which promote tumor aggressiveness)." (PMID 41462933, 2025). "They displayed low levels of Ki67, Olig2, and DCX and higher levels of the mature neuronal marker NeuN, suggesting that overexpression of Foxr2 alone may lead to lesions that harbor differentiated cells and fewer proliferative or stem-like tumor cells." (PMID 39495206, 2025). "FOXR2 expression was also elevated in HL tissues and promoted tumor growth in HL cell lines." (PMID 39866234, 2025). "The mechanisms by which FOXR2 promotes tumor growth are not well understood." (PMID 39866234, 2025). "Specific tumor types are associated with preferential mechanisms of FOXR2 activation, utilization of upstream non-canonical non-coding exons, and patient outcomes." (PMID 40237561, 2025). "The preferential mechanisms of FOXR2 activation varied by tumor type." (PMID 40237561, 2025). "The tumor’s methylation profile also matched with PB, FOXR2." (PMID 38253790, 2024). "More recently, an oligoneural/NB-FOXR2 (NB forkhead box R2) CNS primitive neuroectodermal tumor type-specific model was generated by activating N-RAS in Olig2+/ Sox10+ (oligodendrocyte transcription factor /sex-determining region Y box 10) oligoneural precursor cells of embryonic zebrafish." (PMID 30279402, 2018). "miR-202 may function as a tumor suppressor in EAC tumor growth by targeting FOXR2 oncogene, which may provide new insights into the molecular mechanism and new targets for treatment of EAC." (PMID 28827892, 2017). "Recently, it has been demonstrated that FoxR2 could act with Myc to promote tumor cell proliferation." (PMID 28915588, 2017). "The hedgehog signaling pathway may be essential for FOXR2-induced tumor growth." (PMID 39866234, 2025). "Optimal treatment strategies for this hybrid histological HGG and molecular CNS NBL FOXR2 tumor demand further investigation which may involve assessing the functional impact of FOXR2 activation, known to stabilize cMYC, on global methylome changes in neural progenitor cells." (PMID 35403869, 2022). "The vectors carrying Foxr2 and Akaluc expressed GFP downstream from a modified 2A peptide (PQR), allowing immunochemical detection of tumor cells with GFP." (PMID 39495206, 2025). "DNA methylation profiling can recognize this tumor type, while RNA NGS can be used to detect the FOXR2 rearrangement." (PMID 37658995, 2024). "The initial (pre-methylation profiling) diagnosis, when known, suggested a CNS embryonal tumor, either NOS or a CNS neuroblastoma, FOXR2-activated." (PMID 38500181, 2024). "We found that ATP8B3, FOXR2, FRG2 and HIST1H1A gene silencing significantly enhanced TNBC cells tumor-initiating capacity as well as expression of the TNBC stemness marker, EPCR, thereby defining a new role for these genes in stemness regulation." (PMID 37932309, 2023).
tumor (continued). "Additionally, FOXR2 activates the ETS transcriptional pathways, contributing to tumor development, and influences MAPK signaling, underscoring its role as a widespread oncogene." (PMID 39866234, 2025). "Recent studies have elucidated FOXR2-related pathways and their involvement in both tumor and non-tumor diseases." (PMID 39866234, 2025). "Inference of copy-number alterations revealed that all models displayed some degree of chromosomal abnormalities, including the ones induced by Foxr2 alone, despite their lack of bona-fide proliferating tumor lesions." (PMID 39495206, 2025). "In contrast, Foxr2 p53LOF led to high-grade aggressive tumors with 50% penetrance, appearing as large GFP+ lesions in the striata of symptomatic mice, displaying infiltrative margins, and containing pleiomorphic and occasionally multinucleated tumor cells." (PMID 39495206, 2025). "Remarkably, the three infant tumours that shared FOXR2 rearrangement, but not the older FOXR2-mutant case, were also characterised by an unusual fibro-adenomatoid morphological pattern." (PMID 40442086, 2025). "Moreover, ATP8B3, FOXR2, FRG2 also decreased tumor response to paclitaxel in vivo, in preclinical models of TNBC tumorigenesis." (PMID 37932309, 2023). "However, the oncogenic significance of FOXR2 in all malignancies is not fully understood, nor are the mechanisms by which it promotes tumor growth." (PMID 39866234, 2025). "The absence of this fingerprint in FOXR2+ DIPGs, FOXR2+ EC-NB, and a cell line transduced with FOXR2 suggests that this fingerprint is not likely to be a consequence of FOXR2 activation and instead may be maintained from the tumor lineage of origin." (PMID 39495206, 2025).
CNS tumors (10 papers, 2020 to 2025). "In summary, our findings demonstrate that CNS tumors with FOXR2 overexpression exhibit diverse histopathologic, molecular, and clinical features." (PMID 40237561, 2025). "Histopathologic, molecular, imaging, and clinical data of 42 CNS tumors with FOXR2 overexpression identified through screening institutional datasets and published institutional cases were analyzed." (PMID 40237561, 2025). "Detailed genomic, transcriptomic, and epigenomic analyses were performed to elucidate the molecular mechanisms of FOXR2 activation in specific CNS tumor types and the downstream effects of FOXR2 activation." (PMID 40237561, 2025). "To understand the landscape of CNS tumors with FOXR2 overexpression, we screened the institutional whole-transcriptome gene expression (RNA-seq) datasets to identify tumors with FOXR2 overexpression." (PMID 40237561, 2025). "CNS tumors with FOXR2 overexpression manifest significant histological, molecular, imaging, and clinical diversity." (PMID 40237561, 2025). "Within the 2021 classification of CNS tumors, two novel embryonal tumors have been added: CNS neuroblastoma, FOXR2-activated and CNS tumor with BCOR internal tandem duplication." (PMID 37658995, 2024). "Our results support our hypothesis that CNS tumors with FOXR2 overexpression exhibit diverse histopathologic, molecular, and clinical features." (PMID 40237561, 2025). "We hypothesized that CNS tumors with FOXR2 overexpression exhibit diverse histopathologic, molecular, and clinical features." (PMID 40237561, 2025). "Our findings support the hypothesis that CNS tumors with FOXR2 overexpression exhibit diverse histopathologic, molecular, and clinical features, indicating that FOXR2 alterations are not pathognomonic of CNS NB-FOXR2." (PMID 40237561, 2025). "The 2021 update to the World Health Organization (WHO) classification of CNS tumors saw the incorporation of several new CNS embryonal tumors subtypes, including: cribriform neuroepithelial tumor; CNS neuroblastoma, FOXR2-activated; and CNS tumor with BCOR internal tandem duplication." (PMID 38500181, 2024). "While rare, a PPTID in this cohort suggests that CNS tumors with FOXR2 overexpression are not necessarily histologically high-grade." (PMID 40237561, 2025). "We screened an additional 183 pediatric HGG samples and 22 CNS tumors and did not observe another L1/FOXR2 fusion, likely due to low L1 activity in CNS tumors." (PMID 35403869, 2022). "However, a comprehensive understanding of the landscape for CNS tumors exhibiting FOXR2 activation is lacking." (PMID 40237561, 2025). "However, we observed the inclusion of upstream non-canonical exons in the FOXR2 transcripts in CNS tumors with FOXR2 overexpression." (PMID 40237561, 2025). "We first looked at the downstream effects of FOXR2 activation in CNS tumors at the DNA methylation level by comparing the DNA methylome profiles of tumors with FOXR2 overexpression in our cohort (n = 30 with sufficient data quality) with those of DMGs without FOXR2 activation (n = 25)." (PMID 40237561, 2025).
cancer (5 papers, 2017 to 2025). A tumor composed of atypical neoplastic, often pleomorphic cells that invade other tissues. "This review delves into the mechanisms underlying FOXR2 dysregulation during oncogenesis and its implications for cancer diagnosis, prognosis, and treatment." (PMID 39866234, 2025). "FOXR2 also has potential as a diagnostic and prognostic biomarker and a therapeutic target for cancer patients." (PMID 39866234, 2025). "High FOXR2 mRNA levels in serum correlate with increased expression of cancer markers CA199, SCCA, CA125, and CEA, and are associated with poor clinical outcomes and prognosis in uterine malignancies." (PMID 39866234, 2025). "Detecting FOXR2 expression or specific alterations in cancer tissues may also serve as a diagnostic tool for particular cancer types or subtypes, allowing for more precise and tailored treatment strategies." (PMID 39866234, 2025). "Finally, somatic mutations in the FOXR2 gene can lead to changes in its function or expression levels, further contributing to cancer development and progression." (PMID 39866234, 2025). "Such transcriptional dysregulation results in elevated or inappropriate expression of FOXR2 in cancer cells." (PMID 39866234, 2025). "Continued research and innovative strategies are crucial for translating these models into clinical practice, aiming to improve outcomes for patients with FOXR2-driven cancers." (PMID 39866234, 2025). "In conclusion, the integration of FOXR2 and other key molecular markers into personalized medicine strategies has the potential to transform cancer care by providing tailored treatment options that address the unique characteristics of each patient’s disease." (PMID 39866234, 2025). "In this article, we review the aberrant expression, molecular mechanism, and clinical significance of FOXR2 in cancer." (PMID 39866234, 2025). "Its overexpression leads to increased cell proliferation, survival, and metastatic potential, making FOXR2 a potential target for cancer therapy." (PMID 39866234, 2025). "This crosstalk amplifies the oncogenic effects of FOXR2 dysregulation, promoting cancer progression." (PMID 39866234, 2025). "Understanding these key points of FOXR2 dysregulation is crucial for identifying potential therapeutic targets and developing strategies to counteract its oncogenic effects in cancer." (PMID 39866234, 2025). "FOXR2 has been therefore suggested to function similarly to cancer–testis antigen genes, which are located on chromosome X, expressed in the testis, and escape silencing through hypomethylation, leading to aberrant activation in cancers." (PMID 39495206, 2025). "Its regulation by miR-202 and potential as a therapeutic target highlights the importance of understanding FOXR2’s mechanisms in cancer biology." (PMID 39866234, 2025). "Targeting FOXR2 activity presents a promising approach for treating cancers where it’s a key player." (PMID 39866234, 2025). "We used a combination of Mesh and free keywords such as FOXR2, cancer, and therapeutic as part of the search strategy." (PMID 39866234, 2025). "FOXR2 expression identifies pediatric cancer patients with low 10-year overall survival rates of 53% to 59%, regardless of other risk factors." (PMID 39866234, 2025). "Molecular therapy models for targeting FOXR2 in cancer treatment include RNA interference (RNAi) therapy, CRISPR-Cas9 gene editing, small molecule inhibitors, and antibody-based therapies." (PMID 39866234, 2025). "Abnormal epigenetic regulation can lead to the overexpression of FOXR2 in cancer cells, contributing to tumorigenesis." (PMID 39866234, 2025). "Post-translational modifications, such as phosphorylation, can also impact FOXR2’s stability and activity, further influencing its function in cancer cells." (PMID 39866234, 2025). "CRISPR-Cas9 allows precise gene editing to knock out FOXR2, offering insights into its role in cancer and serving as a potential therapeutic strategy." (PMID 39866234, 2025).
cancer (continued). "Their pan-cancer study across thousands of samples revealed FOXR2 overexpression in most cancers due to a novel, hypomethylated promoter essential for cancer cell proliferation." (PMID 39866234, 2025). "The elevated levels of FOXR2 protein contribute to the malignant behavior of cancer cells, promoting uncontrolled proliferation and survival." (PMID 39866234, 2025). "The identification of FOXR2 as a key player in specific cancer types or subgroups contributes to the development of such personalized medicine strategies." (PMID 39866234, 2025). "Changes in these modifications, such as phosphorylation, can impact the stability, localization, and activity of the FOXR2 protein, contributing to its dysregulation in cancer." (PMID 39866234, 2025). "In this review, we summarize the recent findings on the roles and mechanisms of FOXR2 in cancer and highlight its clinical significance as a biomarker and a target for cancer treatment." (PMID 39866234, 2025). "While FOXR2’s role has been extensively studied in various cancers, its specific involvement in Hodgkin lymphoma (HL) is less clear." (PMID 39866234, 2025). "Moreover, the involvement of FOXR2 in critical cancer-related processes, such as cell proliferation, apoptosis, and DNA damage response, highlights its potential as a therapeutic target." (PMID 39866234, 2025). "Understanding the regulatory mechanisms of FOXR2 could provide new insights into cancer biology and aid in the development of targeted treatments." (PMID 39866234, 2025). "However, cancer patients with higher FOXR2 expression levels often have a better overall survival rate (OS)." (PMID 39866234, 2025). "Furthermore, it was demonstrated that 8% of tumors, or more than 70% of all cancer lineages, showed signs of FOXR2 expression." (PMID 39866234, 2025). "In short, FOXR2 is a significant prognostic biomarker and therapeutic target in various cancers." (PMID 39866234, 2025). "FOXR2 dysregulation is involved in many aspects of cancer progression, such as altering oncogenic pathways, escaping apoptosis, enhancing drug resistance, inducing autophagy, facilitating epithelial to mesenchymal transition, improving DNA repair, and modifying cancer stem cell properties." (PMID 39866234, 2025). "Additionally, these malignancies frequently exhibit chromosomal rearrangements involving the FOXR2 gene, leading to increased FOXR2 expression, a genetic signature common to these types of cancers." (PMID 39866234, 2025). "FOXR2 dysregulation in cancer involves several critical mechanisms." (PMID 39866234, 2025). "One of the FOX proteins, FOXR2, has been identified as an oncogene, a gene that can cause cancer when mutated or overexpressed, which promotes the development of some cancers FOXR2 is located on the X chromosome at Xp11.21 and encodes a TF that is normally expressed only in the testis." (PMID 39866234, 2025). "Consequently, the discovery of FOXR2’s hijacking of ETS transcription circuits shows how TF families collaborate to promote cancer and expands the methods known to activate ETS TFs." (PMID 39866234, 2025). "Recent studies proposed that FOXR2 was aberrantly expressed in several cancers." (PMID 28827892, 2017). "In summary, FOXR2, identified as an oncogene within the FOX gene family, plays a crucial role in developing various endoderm-derived organs and has been linked to numerous malignant tumors, making it a potential target for cancer diagnosis, prognosis, and treatment." (PMID 39866234, 2025). "We found that several of these genes (ATP8B3, FOXR2, FRG2, HIST1H4A) act as cancer stemness negative regulators." (PMID 37932309, 2023). "FOXR2 is a member of the FOX protein family and plays important roles in the development and progression of cancers." (PMID 28827892, 2017). "Additionally, FOXR2 contributes to the epithelial-mesenchymal transition (EMT), a process essential for cancer metastasis." (PMID 39866234, 2025).
cancer (continued). "Together, FOXR2 and 3D-PDU present a potential method for detecting these cancers." (PMID 39866234, 2025). "Collectively, and combined with our findings, showing increased paclitaxel resistance in these gene KOs, our results define ATP8B3, FOXR2, FRG2 and HIST1H4A as cancer stemness negative regulators, consistent with a role for these genes as potential drug (paclitaxel) sensitizers." (PMID 37932309, 2023). "Having shown that ATP8B3, FOXR2, FRG2 and HIST1H4A KOs increased paclitaxel resistance and cancer stemness in vitro, we next investigated whether these KOs could also regulate paclitaxel effects in vivo." (PMID 37932309, 2023). "Interestingly, we found several of these genes (ATP8B3, FOXR2, FRG2, HIST1H4A) to act as cancer stemness regulators, able to regulate cancer stem cell self-renewal activity and expression of the endothelial protein C receptor (EPCR), a specific stemness marker for TNBC." (PMID 37932309, 2023).
FOXR2 also shares sentences with these, for which no sentence is quoted: ependymoma (3 papers); Ewing Sarcoma Family Tumor (3); malignant peripheral nerve sheath tumor (3); atypical teratoid rhabdoid tumor (2); CNS-primitive neuroectodermal tumor (2); glioblastoma (2); sarcoma (2); astrocytoma (1); bladder cancer (1); breast adenocarcinoma (1); Burkitt lymphoma (1); childhood cancers (1); diffuse intrinsic pontine glioma (1); Endometrial Adenocarcinoma (1); epilepsy (1); Ewing sarcoma (1); extraventricular neurocytoma (1); glioneuronal tumor (1); lymphoma (1); multiple myeloma (1); oligodendroglioma (1); pineal tumor (1); pineocytoma (1); primitive neuroectodermal tumor (1); rhabdoid tumor (1).